ITCH (itchy E3 ubiquitin protein ligase)
Diseases named in the same sentence as ITCH in open-access papers (continued):
Sharing a sentence is not in itself a finding about the gene and the disease.
hepatocellular carcinoma (17 papers, 2017 to 2025). A malignant tumor that arises from hepatocytes. "In prior studies, it was found that the circ-ITCH SNPs rs10485505 and rs4911154 were strongly related to increased hepatocellular carcinoma risk." (PMID 37370928, 2023). "Rs4911154, an SNP located in circ-ITHC, was previously reported to be significantly associated with an increased risk of hepatocellular carcinoma because circ-ITCH may exert an inhibitory effect on HCC19." (PMID 34531437, 2021). "YOD1 regulates the stability of PML/RARα, CDK1, and ITCH, promoting malignant phenotypes in acute promyelocytic leukemia, triple-negative breast cancer, and hepatocellular carcinoma, respectively." (PMID 40274778, 2025). "Circ ITCH expression is elevated in patients with hepatocellular carcinoma compared with healthy controls and correlates with increased AST and ALT levels." (PMID 41465470, 2025). "Low levels of circ-ITCH expression were first observed in oesophageal cancer, followed by colon, hepatocellular carcinoma, and lung cancer." (PMID 37370928, 2023). "circHIPK3 is a circRNA that functions as a circular sponge for miR-124 in hepatocellular carcinoma, and circ-ITCH is another circRNA that inhibits the progression of bladder cancer by acting as a sponge for miR-17 and miR-224." (PMID 35328383, 2022). "Otherwise, a significant upregulation of miR-411 was found in hepatocellular carcinoma, which promoted the proliferation and anchorage-independent growth of hepatocellular carcinoma cells via suppressing ITCH, a putative tumor suppressor." (PMID 34606414, 2021). "According to a study that validates our findings, circ-ITCH expression was considerably lower in hepatocellular carcinoma (HCC) tissues than in neighbouring tissues, and circ-ITCH expression levels were higher in HCC tissues compared to adjacent tissues." (PMID 37370928, 2023). "On the other hand, miR-411-5p as an oncogene targeted FOXO1 and ITCH to promote cell cycle process and proliferation in NSCLC and hepatocellular carcinoma." (PMID 30390072, 2019). "Until now, researchers have discovered several novel circRNAs working as a miR-7 sponge, such as circ_0000735 in prostate cancer, circ-ITCH in osteosarcoma, circ-TFCP2L1 in breast cancer, and circ_0015756 in hepatocellular carcinoma (HCC)." (PMID 33673265, 2021).
bladder cancer (14 papers, 2018 to 2023). "circ-ITCH and circHIPK3 express lower in bladder cancer tissues, and negatively associate with grade, stage as well as lymph node metastasis of bladder cancer patients." (PMID 32019579, 2020). "Upregulated circPRMT5 in serum and urinary exosomes and downregulated circ-ITCH, circHIPK3 and circMTO1 in bladder cancer tissues are positively associated with grading, staging, infiltration, and lymph node metastasis in bladder cancer patients." (PMID 31808751, 2019). "For example, circ-ITCH is downregulated in bladder cancer tissues and cell lines, and patients with low circ-ITCH expression are significantly associated with a shorter OS." (PMID 30064463, 2018). "In the case of ITCH, the pro-autophagic and oncogenic roles in breast, prostate, and bladder cancer cells have been found and, thus, suggest ITCH inhibitors as the potential therapeutic tool in these cancer." (PMID 36918822, 2023). "Patients with lower circ-ITCH expression had a poorer prognosis in bladder cancer, and higher levels of circPRCKI displayed as a worse progression marker in lung adenocarcinoma." (PMID 31928527, 2020). "Circ-ITCH, the circularized product from several exons of itchy E3 ubiquitin protein ligase homolog (ITCH), has been reported to be downregulated in bladder cancer (BCa)tissues and correlated with the histological grade and shortened survival of BCa patients." (PMID 30999909, 2019). "The anti-tumor activity of the circRNA itchy E3 ubiquitin protein ligase (circ-ITCH) was demonstrated in human bladder cancer tissue and in human bladder cancer cell lines EJ and T24." (PMID 31080413, 2019). "Circ-ITCH is generated from itchy E3 ubiquitin protein ligase (ITCH) coding region and is involved in bladder cancer." (PMID 30112184, 2018). "Decreased expression of circ-ITCH was correlated with shortened survival in bladder cancer patients." (PMID 30112184, 2018). "For example, a positive correlation was analyzed between serum circPRMT5 and metastasis of bladder cancer; negative associations among circ-ITCH, circHIPK3 and cancer grade, stage as well as lymph node metastasis of bladder cancer were identified gradually." (PMID 32019579, 2020). "For example, circRNA‐000284 is an oncogene and promotes the progression of CC via the miR‐506/Snail‐2 pathway (Ma, Yao, Yu, Chen, & Li, 2018), whereas circ‐ITCH is a tumor suppressor by suppressing the activity of miR‐17/miR‐224 and upregulating their target genes in bladder carcinoma." (PMID 31256433, 2020). "However, the role of circ-ITCH in bladder cancer (BCa) was not reported." (PMID 29386015, 2018).
melanoma (12 papers, 2019 to 2025). A malignant, usually aggressive tumor composed of atypical, neoplastic melanocytes. "Here, we report that in response to proinflammatory cytokines, BRAF is subjected to lysine 27-linked poly-ubiquitination in melanoma cells by the ITCH ubiquitin E3 ligase." (PMID 31015455, 2019). "In melanoma cells, ITCH-mediated BRAF ubiquitination is pivotal in coordinating the signals between cytokines and MAPK pathway activation." (PMID 37760946, 2023). "Circular RNA itchy E3 ubiquitin protein ligase (circ-ITCH) has proven to be a suppressor in various cancers such as melanoma and OC." (PMID 35550610, 2022). "And it is been found that ITCH is a downstream target of miR-10b which promoted melanoma progression by repressing ITCH." (PMID 35847032, 2022). "Its knockdown results in ITCH-mediated suppression of proliferation, migration and invasion in melanoma cells." (PMID 33968718, 2021). "In melanoma, it was described that ITCH can directly interact with BRAF and promotes its lysine 27-linked polyubiquitination." (PMID 33800394, 2021). "Physiologically, proinflammatory cytokines activate ITCH to maintain BRAF activity and to promote proliferation and invasion of melanoma cells, whereas the ubiquitination-deficient BRAF mutant displays compromised kinase activity and reduced tumorigenicity." (PMID 31015455, 2019). "In accordance with a pro-survival role of ITCH in melanoma cells, we found that overexpression of ITCH activated MEK/ERK, and supported TPA-independent growth of melan-a cells." (PMID 31015455, 2019). "Notably, ubiquitination of endogenous BRAF was induced by TNFα or IL-1β treatment in both melanocytes and melanoma cells, while depletion of ITCH abrogated TNFα-stimulated BRAF ubiquitination." (PMID 31015455, 2019). "The addiction of melanoma cells to the ITCH–BRAF signaling indicates that ITCH could be a potent therapeutic target for BRAFWT-expressing melanomas." (PMID 31015455, 2019). "To assess the role of ITCH in TNFα-triggered BRAF activation, we found that p-MEK and p-ERK were refractory to TNFα treatment in ITCH-depleted melanoma cells." (PMID 31015455, 2019). "In support of a potential role of ITCH in controlling BRAF function, we found that in melanoma cells, depletion of ITCH suppressed proliferation and 3D spheroid formation of WM1346 cells." (PMID 31015455, 2019). "To this end, we demonstrated that endogenous ITCH interacted with BRAF in both BRAFWT-expressing WM1346 and BRAFV600E-expressing A375 melanoma cells." (PMID 31015455, 2019). "Collectively, our study reveals a pivotal role for ITCH-mediated BRAF ubiquitination in coordinating the signals between cytokines and the MAPK pathway activation in melanoma cells." (PMID 31015455, 2019). "Our results coherently demonstrate that ITCH positively regulates the BRAF/MEK/ERK signaling cascade and facilitates the survival of BRAFWT melanoma cells." (PMID 31015455, 2019). "We demonstrate that ITCH facilitates the survival of BRAFWT-expressing melanoma cells, supporting an oncogenic function of ITCH in BRAFWT melanoma." (PMID 31015455, 2019). "Moreover, the binding of endogenous BRAF with 14–3–3 proteins was attenuated after melanoma cells were treated with TNFα, which were shown to activate JNK/ITCH to facilitate BRAF ubiquitination." (PMID 31015455, 2019). "In melanoma cells treated with proinflammatory cytokines, the HECT domain-containing E3 ligase ITCH catalyzes the non-degradative K27-linked ubiquitination of BRAF, which leads to PP2A recruitment, 14-3-3 dissociation, and sustained BRAF/MEK/ERK pathway activation." (PMID 36585710, 2022). "Similarly, depletion of ITCH in melanocytes and BRAFWT-expressing WM3918, WM1346, M245, and IPC-298 melanoma cells led to a remarkable reduction of p-MEK and p-ERK levels." (PMID 31015455, 2019).
melanoma (continued). "It is noteworthy that although TNFα promoted BRAF ubiquitination in BRAFV600E-expressing 1205Lu melanoma cells, the treatment only moderately affected MEK/ERK activities, which is consistent with the results that p-MEK/p-ERK levels were insensitive to ITCH knockdown." (PMID 31015455, 2019). "Here, the authors show that in response to pro-inflammatory cytokines, ITCH mediates a non-proteolytic ubiquitination and activation of BRAF, which in turn sustains MEK/ERK signaling to facilitate melanoma cell growth." (PMID 31015455, 2019).
gastric cancer (10 papers, 2018 to 2025). A primary or metastatic malignant neoplasm involving the stomach. "The results of these studies indicate that ITCH may be associated with gastric cancer progression." (PMID 33060778, 2020). "By controlling the Wnt/-catenin pathway, Cir-ITCH prevents gastric cancer migration, invasion, and proliferation." (PMID 39293372, 2024). "The results showed that patients with higher cir-ITCH expression levels in gastric cancer tissues exhibited substantial upregulation of linear ITCH." (PMID 33060778, 2020). "To study the function of cir-ITCH in gastric cancer, the cir-ITCH overexpression plasmid was transfected into MKN45 and AGS cells, and we observed that cir-ITCH expression was significantly increased in both cell lines." (PMID 33060778, 2020). "In summary, cir-ITCH was shown to prevent gastric cancer tumourgenesis through the Wnt/β-catenin signalling pathway by sequestering miR-17." (PMID 33060778, 2020). "In our present study, we assessed the expression of cir-ITCH in gastric cancer and examined the prognostic potential of cir-ITCH in gastric cancer." (PMID 33060778, 2020). "Taken together, these results showed that cir-ITCH can attenuate gastric cancer cell proliferation, migration and invasion by sequestering miR-17." (PMID 33060778, 2020). "We observed that cir-ITCH expression was higher in the adjacent normal mucosa compared to that observed in matched gastric cancer samples." (PMID 33060778, 2020). "In summary, our results showed that cir-ITCH is a prognostic marker that is downregulated in gastric cancer and that cir-ITCH can prevent gastric cancer tumourigenesis by sequestering miR-17 through the Wnt/β-catenin pathway." (PMID 33060778, 2020). "To further investigate cir-ITCH expression in gastric cancer, we examined cir-ITCH expression in human gastric cancer samples and paired adjacent normal mucosa samples by TaqMan-based RT-qPCR assays." (PMID 33060778, 2020). "In gastric cancer, for example, the AXIN1-295aa protein encoded by CircAXIN1 disrupts the β-catenin degradation complex and promotes tumor invasion, whereas circ-ITCH inhibits pathway activity by sponging miR-17 and upregulating ITCH expression." (PMID 41050070, 2025). "Similarly, circ-ITCH, found in gastric cancer cells, acts as a sponge of miR-199a-5p and, through this function, suppresses metastasis of gastric cancer." (PMID 38500957, 2024). "As cir-ITCH shares some miRNA binding sites with the 3′UTR of ITCH and can regulate linear ITCH expression in different cancers, we inferred that cir-ITCH may be a crucial gene in the development of gastric cancer." (PMID 33060778, 2020). "Through RTq-PCR assays, we observed that cir-ITCH expression was attenuated in gastric cancer cell lines and tissues, with cir-ITCH expression in gastric cancer tissues with lymph node metastasis being considerably lower than that observed in gastric cancer tissues without lymph node metastasis." (PMID 33060778, 2020). "In vitro, cir-ITCH was shown to significantly reduce the tumourigenesis of gastric cancer." (PMID 33060778, 2020). "Unfortunately, the possible mechanism regarding how ITCH affects gastric cancer tumourigenesis remains unclear." (PMID 33060778, 2020). "Therefore, in our present study, we investigated the expression and function of cir-ITCH in gastric cancer." (PMID 33060778, 2020). "Expression of CBL is variable in different gastric cancer cell lines, whereas the expression of ITCH is increased in the same group of gastric cancer cell lines, suggesting that the ITCH-mediated and CBL-mediated c-FLIP degradation processes are not operational in gastric cancer." (PMID 29374180, 2018). "Indeed, our results showed that cir-ITCH could inhibit gastric cancer tumourigenesis by promoting linear ITCH expression through miR-17 in vivo and vitro." (PMID 33060778, 2020). "In addition, we observed that cir-ITCH could significantly reduce the migration and invasion of gastric cancer cells." (PMID 33060778, 2020).
gastric cancer (continued). "For instance, circ-ITCH affects the EMT pathway and suppresses metastasis of gastric cancer by sponging miR-199a-5p and thereby increasing Klotho expression." (PMID 35327551, 2022). "In gastric cancer, ASPP2 inhibited ubiquitin-dependent degradation of Smad7 by interacting with ITCH, leading to the suppression of TGF-β1-Smad2/3 signaling, which reduced migration and invasion of gastric cancer cells both in vitro and in vivo." (PMID 32420372, 2020). "First, we examined cir-ITCH expression in gastric cell lines using TaqMan-based RT-qPCR assays and observed that cir-ITCH expression was decreased in the gastric cancer cell lines (AGS and MKN45) compared to that observed in normal gastric mucosa cells (GES1)." (PMID 33060778, 2020). "In contrast, expression of ITCH and CBL, the ubiquitin E3 ligases that have been shown to promote polyubiquitination and proteosomal degradation of c-FLIP25,26, are normal or increased in the same gastric cancer tissues 43–45." (PMID 29374180, 2018). "In summary, we identify DTX1, but not CBL or ITCH, as the E3 ligase regulating c-FLIP protein stability in gastric cancer cells." (PMID 29374180, 2018).
prostate carcinoma (9 papers, 2016 to 2023). A carcinoma that arises from epithelial cells of the prostate gland. "So far, circ-ITCH has been proved to be implicated in prostate cancer, ovarian cancer, bladder cancer, breast cancer, lung cancer, oral squamous cell carcinoma, gastric cancer, hepatocellular carcinoma, glioma, and multiple myeloma." (PMID 33623789, 2021). "In prostate cancer tissues and PC cell lines, circ-ITCH expression levels were significantly lower than in adjacent normal tissues and human prostate epithelial cells, according to prostate cancer." (PMID 37370928, 2023). "We began our validation by using siRNA to knockdown SPOP expression in prostate cancer cells followed by measuring the expression of ITCH by Western blot." (PMID 34322378, 2021). "Our study investigated the role and mechanism of cir-ITCH in PCa and provided evidence indicating that cir-ITCH functions as tumor suppressor in prostate cancer cells via the Wnt/β-catenin and PI3K/AKT/mTOR pathways in an AR-independent manner." (PMID 32904490, 2020). "Specifically, ART regulates the lncRNA UCA1/miR-184/BCL-2 axis, to inhibit prostate cancer, while the has-circ-0043256/miR-1252/ITCH axis was involved in the treatment of non-small cell lung cancer by CA." (PMID 31178721, 2019). "Specifically, 9F7-F11-induced HER3 ubiquitination and degradation in pancreatic, breast and prostate cancer cell lines was driven mainly by the itchy E3 ubiquitin ligase (ITCH/AIP4)." (PMID 27203743, 2016). "However, the role of cir-ITCH in prostate cancer, especially in CRPC, has not been well described." (PMID 32904490, 2020).
ovarian carcinoma (8 papers, 2020 to 2025). A malignant neoplasm originating from the surface ovarian epithelium. "Currently, the association between the expression of circ-ITCH and the ovarian cancer patient overall survival has been analyzed." (PMID 32714095, 2020). "In this study, we found that circ-ITCH low expression was associated with the poor prognosis of the ovarian cancer patients." (PMID 32714095, 2020). "As is demonstrated in recent studies, the expression level of circ-ITCH is decreased in ovarian cancer tissues, this abnormal aspect being closely associated with various clinicopathological characteristics like tumor size, FIGO, TNM stage, and also, with survival rate." (PMID 34207450, 2021). "In vivo experiments show that circ-ITCH suppresses epithelial ovarian cancer cell proliferation and promotes apoptosis through targeting miR-10a-α." (PMID 35327551, 2022). "On the other hand, circ-ITCH, circPLEKHM3, circ_100395, circ_0078607, circATRNL1, circHIPK3, circRHOBTB3, circEXOC6B, circ9119 and CDR1as are among down-regulated circRNAs in ovarian cancer." (PMID 35488239, 2022). "The results showed that circ-ITCH was significantly repressed in ovarian cancer tissues compared with normal tissues." (PMID 32714095, 2020). "In this research, circ-ITCH enormously inhibited invasion and glycolysis of ovarian cancer cells and promoted cell apoptosis, suggesting that circ-ITCH was a tumor suppressor in ovarian cancer in vitro." (PMID 32714095, 2020). "In agreement with our data, circ-ITCH was lowly expressed in ovarian cancer tissues and cells, and overexpression of circ-ITCH triggered the suppression effects on proliferation of ovarian cancer cells." (PMID 32714095, 2020). "Our results suggested that low circ-ITCH expression led to poor prognosis in patients with ovarian cancer." (PMID 32714095, 2020). "Circ-ITCH was down-regulated in ovarian cancer and positively correlated with 5-year overall survival of patients with ovarian cancer." (PMID 32714095, 2020). "Functionally, circ-ITCH overexpression hindered proliferation, invasion, glycolysis and promoted apoptosis of ovarian cancer cells." (PMID 32714095, 2020). "Circ-ITCH suppressed proliferation, invasion, glycolysis, and promoted apoptosis of ovarian cancer cells by modulating the miR-106a/CDH1 axis." (PMID 32714095, 2020). "Functional studies performed in the last years showed that the expression levels of circ-ITCH, circPLEKHM3, and circRNA_100395 were significantly lower in ovarian cancer and validated the ceRNA hypothesis." (PMID 34207450, 2021). "Together, these data suggested that upregulation of circ-ITCH could block the growth of ovarian cancer cells by regulating the miR-106a/CDH1 axis in vivo." (PMID 32714095, 2020). "Additionally, ovarian cancer patients with low circ-ITCH level (n = 26) had a lower 5-year survival rate in comparison to those patients with high circ-ITCH level (n = 19) (P = 0.0257)." (PMID 32714095, 2020). "Given the targeting relationship between miR-106a and circ-ITCH or CDH1 in ovarian cancer cells, we further explored whether circ-ITCH could regulate CDH1 expression." (PMID 32714095, 2020). "However, it is still unknown whether circ-ITCH can regulate tumor progression through other regulatory axes in ovarian cancer." (PMID 32714095, 2020). "Thus, we speculated whether circ-ITCH could also play a role in ovarian cancer as a ceRNA." (PMID 32714095, 2020). "Transcriptome analysis and cell experiments have indicated that circ-ITCH is negatively correlated with lncRNA HLUC, and circ-ITCH overexpression may reduce the proliferation of ovarian carcinoma by downregulating lncRNA HULC." (PMID 35327551, 2022).